GATA3 (GATA binding protein 3)
Diseases named in the same sentence as GATA3 in open-access papers (continued):
Sharing a sentence is not in itself a finding about the gene and the disease.
adenocarcinoma (21 papers, 2009 to 2026). A common cancer characterized by the presence of malignant glandular cells. "Adenocarcinoma originating from the anal gland with immunohistochemical expression of GATA3 and TTF-1 (ACAGGT) is a rare entity." (PMID 41907615, 2026). "A transbronchial biopsy from the left lower lobe revealed adenocarcinoma with positive immunostaining for estrogen receptor and GATA-binding protein 3, consistent with metastatic breast cancer." (PMID 41913869, 2026). "Imaging revealed diffuse bone metastases, and bone biopsy confirmed a poorly differentiated adenocarcinoma of breast origin (estrogen receptor, 60%; progesterone receptor, 35%; GATA3 positive)." (PMID 40666594, 2025). "Commonly, GATA-3 expression characterizes tumors arising from skin adnexa, urothelium, salivary glands, and pancreatic ducts, whereas adenocarcinomas of lung, stomach, colon, and prostate showed positivity to a lesser extent." (PMID 29116378, 2018). "Here we evidence Gata-2 and Gata-3 to be up to −12.7-fold down regulated in adenocarcinoma." (PMID 19812696, 2009). "In the case of RECK, CRISPLD2, HPGD, GATA3 and GPC3, the signal related to the expression of the protein was down regulated in more than 45% of adenocarcinomas compared to surrounding healthy pneumocytes." (PMID 24265725, 2013). "Although some nuclei showed PTC-like chromatin clearing, negative staining for TTF1 and GATA3 and the absence of KRAS/NRAS mutations ruled out mesonephric-like adenocarcinoma." (PMID 40959354, 2025). "Mesonephric-like adenocarcinomas are characterized by the expression of GATA3 or TTF1 with the absence of ER/PR expression." (PMID 35053578, 2022). "Several entities were considered in the differential diagnosis, including mesonephric-like adenocarcinoma; however, the absence of characteristic morphologic features and the lack of PAX8 and GATA3 expression did not support this diagnosis." (PMID 41517393, 2025). "Cells of the adenocarcinoma component were CAM.5.2, CK7, CK AE1/AE3, and GATA-3 positive and negative for synaptophysin, chromogranin A, parathormone, parafibromin, thyroglobulin, TTF1, calcitonin, glucagon, S100, PGP-9 and Bcl-2." (PMID 32506375, 2021).
inflammation (14 papers, 2013 to 2025). Aberrant reaction of the microcirculation characterized by movement of fluid and leukocytes from the blood into extravascular tissues. "Experimental depletion of Vγ1+ cells in an animal CRS model reduced eosinophilic inflammation and suppressed T2-associated cytokines (IL-4, IL-5, and IL-13) and GATA3 expression, indicating that defined γδ subsets can potentiate T2-biased inflammation." (PMID 41470145, 2025). "Because GATA3 is involved in both pathways, it seems reasonable to target this molecule when treating patients with an eosinophilic airway inflammation." (PMID 29615049, 2018). "This was the first trial evaluating a GATA3-specific substance in a population of COPD patients with eosinophilic airway inflammation." (PMID 29615049, 2018). "GATA-3 induced steroid-sensitive eosinophilic airway inflammation by enhancing Th2 cell differentiation and Th2 cytokine production, whereas RORγt induced steroid-insensitive neutrophilic airway inflammation by enhancing Th17 cell differentiation and Th17 cytokine production." (PMID 30541898, 2019). "Treatment with crocin led to a decrease in the severity of lung inflammation in OVA-sensitized mice, which is probably through the reduction of the T-bet/GATA-3 ratio, and mir-146a and mir-106a expression level." (PMID 36311189, 2022). "Previous studies have shown that Treg cells lacking Bcl6 overexpress GATA3 (GATA binding protein 3), a Th2-determining transcription factor, thereby aggravating Th2-type airway inflammation." (PMID 40290124, 2025).
renal disease (9 papers, 2011 to 2023). "Optional GATA3 testing was suggested in 2018, except in cases of isolated sensorineural deafness or renal disease with pertinent family history." (PMID 38116790, 2023).
immune dysfunction (5 papers, 2015 to 2024). "GATA-3 upregulation in CD8+ T cells has been identified as a biomarker of immune dysfunction in SSc, resulting in excessive IL-13 production." (PMID 36232733, 2022). "In the current study, upregulation of c-Maf, GATA3, IL-5, and IL-13 in the colonic mucosa of HES goats confirmed that the colonic inflammation in growing goats caused by HES was attributed to the TH2 cytokine pattern, which might be related to the TH2-mediated immune disorder." (PMID 38395946, 2024).
genetic disorder (4 papers, 2017 to 2025). "In summary, we detail a case of HDRS featuring a rare GATA3 mutation at 10p15, aiming to enrich the sparse literature and enhance guidance in managing and counseling the diverse variations of this uncommon genetic disorder." (PMID 41019281, 2025). "Furthermore, accumulating studies have demonstrated that GATA2 and GATA3 are involved in distinct types of inherited diseases as well as carcinogenesis in diverse tissues." (PMID 33803938, 2021).
respiratory diseases (4 papers, 2021 to 2025). "Notably, stable GATA3 levels across time points (< 5% variance) confirmed minimal Th2 skewing, mitigating theoretical concerns regarding vaccine-associated enhanced respiratory diseases." (PMID 40746539, 2025). "Sex hormones (oestrogens and androgens) contribute to the female sex bias in type 2 inflammation associated with respiratory diseases, consistent with recent reports that female lungs harbour greater numbers of GATA-3–dependent group 2 innate lymphoid cells (ILC2s)." (PMID 34512639, 2021).
bacterial infection (3 papers, 2008 to 2024). "The protective effects of the overexpression of T-bet, GATA-3 and TGF-ß on both bacterial infections were negligible." (PMID 32326041, 2020). "Interestingly, we also found there are some hubs only present in the reconstructed network but not in the text like GATA3 and FPR, which would be involved in host defense against bacterial infection and in the clearance of damaged cells." (PMID 18823570, 2008).
benign tumors (2 papers, 2020 to 2023). "When GATA-3 expression (high ≥79.4% vs. low <79.4%) was analyzed in accordance with histological group, the benign tumor group showed a greater number of samples with high expression of GATA-3." (PMID 37483298, 2023).
haematological disease (2 papers, 2020 to 2024). "The transcription factor Gata3 has also been linked to haematological disease and was shown to promote HSC production in the embryo by inducing the secretion of important niche factors." (PMID 31634421, 2020).
colonic polyps (1 paper, 2019). "While a TH2 environment in colonic polyps is consistent with MC expansion, the nature of communication between MCs and Gata3+ lymphocytes, which include T-cells and ILC2s is poorly understood." (PMID 31849960, 2019).
neurodegenerative disease (1 paper, 2024). A disorder of the central nervous system characterized by gradual and progressive loss of neural tissue and neurologic function. "Hence, tailoring GATA3-mediated treatment and management plans for PD specifically and neurodegenerative disease generally becomes plausible as it seems beneficial for patients to manage their symptoms and improve their outcomes." (PMID 39768217, 2024).
GATA3 also shares sentences with these, for which no sentence is quoted: basal cell carcinoma (7 papers); Hypocalcemia (4); renal failure (4); Renal neoplasm (4); cervical squamous cell carcinoma (3); colon adenocarcinoma (3); eczema (3); leiomyosarcoma (3); metabolic disorders (3); oncocytic tumor (3); pancreatic adenocarcinoma (3); papillary carcinoma (3); sweat gland carcinoma (3); T-cell acute lymphoblastic leukemia (3); airway hyperresponsiveness (2); alveolar rhabdomyosarcoma (2); Behcet disease (2); breast (2); congenital ichthyosis (2); cutaneous T-cell lymphoma (2); depression (2); diffuse large B-cell lymphoma (2); endometrial adenocarcinoma (2); epithelial neoplasm (2); fatty liver disease (2); gastrointestinal tumors (2); head and neck neoplasm (2); Hearing impairment (2); Kidney Cyst (2); Leukocytosis (2).
A further 144 diseases each share a sentence with GATA3 in 2 papers or fewer.